ZNF853 (zinc finger protein 853)
Synonyms: DKFZp434J1015
Tractability: No criterion of Open Targets' tractability assessment is met for any kind of drug.
Gene: Protein-coding gene on chromosome 7 (6,615,348 to 6,624,290, forward strand). Ensembl gene ENSG00000236609.
Subcellular location (Human Protein Atlas): Nucleoli
Gene Ontology:
Molecular function: DNA-binding transcription factor activity, RNA polymerase II-specific; RNA polymerase II cis-regulatory region sequence-specific DNA binding
Biological process: regulation of transcription by RNA polymerase II
Cellular component: nucleus
Genetic constraint (gnomAD): Loss-of-function variants: 57 observed, 82.53 expected, observed/expected ratio (o/e) 0.69, 90% interval 0.56 to 0.86. The synonymous counts are far from expectation, so gnomAD's model fits this gene poorly and the ratio says little. Missense variants: 780 observed, 712.36 expected, observed/expected ratio (o/e) 1.1, 90% interval 1.03 to 1.16. Synonymous variants: 446 observed, 344.28 expected, observed/expected ratio (o/e) 1.3, 90% interval 1.2 to 1.4.
Homologues: Orthologues: chimpanzee ZNF853 (99% identical), macaque ZNF853 (97% identical), dog ZNF853 (79% identical), pig ZNF853 (75% identical), guinea pig ZNF853 (75% identical), mouse Zfp853 (73% identical), rat Zfp853 (65% identical), rabbit ZNF853 (63% identical). Paralogues in human: ZKSCAN1 (22% identical), ZKSCAN8 (22% identical), ZKSCAN3 (21% identical), ZKSCAN4 (21% identical), ZNF394 (21% identical), ZSCAN30 (21% identical), ZNF397 (21% identical), ZNF500 (21% identical), ZSCAN25 (21% identical), ZNF263 (21% identical), ZSCAN31 (20% identical), ZSCAN12 (20% identical), and 18 more.